AKT1 (AKT serine/threonine kinase 1)
Diseases named in the same sentence as AKT1 in open-access papers (continued):
Sharing a sentence is not in itself a finding about the gene and the disease.
diabetes (continued). "Herein we show that increasing Akt1 activity in retina/RPE attenuated diabetes-induced retinal molecular alterations and that reduction of Akt1 activity in RPE accelerated retinal pathological vascular damage in diabetic mice." (PMID 36229454, 2022). "Our data support the premise that Akt2 cKO in the RPE has a protective effect against diabetes-induced retinal damage, including infiltration and activation of immune cells, by mediating the Akt1/GSK3β/NF-κB signaling axis." (PMID 36229454, 2022). "Dozens of studies have reported that abnormal AKT1 activates in diabetes, cardiovascular diseases and various cancers." (PMID 28978011, 2017). "AKT1, significantly downregulated in EC, plays an important role in the relationship of AD and diabetes." (PMID 29359159, 2017). "The mRNA expression of the activated lymphocytes showed that diabetes had decreased the Akt1 signaling." (PMID 25009576, 2014). "mRNA expression of the activated lymphocytes showed that diabetes impaired the Akt1 (234 ± 9.5), CD28 (229 ± 14) and Cdc42 (33 ± 6.5) signaling compared to those of the control group [Akt1 (252 ± 12), CD28 (235 ± 10), Cdc42 (45 ± 5.0)]." (PMID 25009576, 2014). "Wnt1 has previously been shown to activate the PI 3-K/Akt1 pathway during serum deprivation, ischemic injury, experimental diabetes as well as tumor growth." (PMID 22388478, 2012). "We and others have shown that diabetes depresses retinal insulin signaling with decreased kinase activities of the insulin receptor and downstream signaling proteins including Akt1 and Akt3." (PMID 22046295, 2011). "KCLE also improves diabetes by regulating AKT1, TNF, EGFR, and GSK3β." (PMID 40076380, 2025). "Moreover, in silico studies have confirmed thymoquinone’s strong binding affinity to microbial virulence regulators (e.g., LasR, PqsR) and human diabetes-related targets (e.g., AKT1), supporting its dual application as an antidiabetic and antimicrobial agent." (PMID 40969600, 2025). "Additionally, the three disease targets with the highest connectivity values in the string network, STAT3, BCL2, and AKT1, also mediate multiple diabetes-related signaling pathways and are key targets in the treatment of diabetes." (PMID 40733369, 2025). "To examine whether the diabetes-induced increase in the expression of pro-inflammatory proteins in the RPE is influenced by Akt1 downregulation, we evaluated the level of Akt1 downstream targets." (PMID 36229454, 2022). "Thus, it is possible that Akt2 knockout in the RPE has a protective effect against diabetes through upregulated Akt1, further inhibiting a GSK3β/NF-κB-regulated inflammatory response." (PMID 36229454, 2022). "As for the molecular mechanism of anti-diabetes, five compounds with better activity in vitro were selected to explore their effects on the AKT1, IL-6 and VEGFA mRNA expression, indicating that their anti-diabetes mechanism was related to PI3K-AKT signaling pathway." (PMID 36559019, 2022). "Circulating EVs from people with diabetes carry increased levels of specific phosphorylated kinases (i.e., AKT1, GSK3B, LYN, MAP2K2, MYLK, and PRKCD) and could potentially distribute activated kinases systemically." (PMID 35628588, 2022). "This suggests that modulation of Akt1 in the retina/RPE may play an important role in diabetes-induced early retinal molecular alterations such as inflammation and oxidative stress and pathological changes such as capillary degeneration and pericyte loss." (PMID 36229454, 2022). "All these data indicate that AKT1 may play a therapeutic role in diabetes development, as confirmed by the upregulation of the akt1 gene expression by the SkQ1 pre-therapy." (PMID 34829620, 2021). "Blood flow and other physiological stimuli activate eNOS viaPI3 kinase/AKT1; therefore, an impairment of this signaling mechanism in diabetes may have broad implications for vascular dysfunction." (PMID 24734227, 2014).
diabetes (continued). "Overall results suggest that AKT1 can compensate for an AKT2 deficiency with regard to glucose homeostasis and diabetes, and that AKT isoforms may have complementary and compensatory roles in glucose homeostasis in vivo." (PMID 22680924, 2012). "As previously demonstrated, Akt1 and Akt3 activities in the retina were reduced by diabetes." (PMID 22046295, 2011). "The ablation of individual AKT isoforms exhibits distinct phenotypes in gene knockout mice: Akt1 knockout mice show growth perinatal lethality and elevated apoptosis; Akt2 knockout mice exhibit a diabetes-like phenotype; and Akt3 knockout mice have small brains with mild neurologic defects." (PMID 37998329, 2023). "COMF and its active components quercetin, kaempferol, isorhamnetin, luteolin and apigenin could regulate AKT1, VEGFA and IL-6 mRNA levels and improve the dysregulation of PI3K-AKT pathway signaling to intervene the inflammation and trauma manifested during the development of diabetes." (PMID 36559019, 2022). "Normalization of blood glucose and increased local retinal insulin levels both reversed the diabetes-induced retinal cell death in correlation with the reversal of retinal insulin signaling as demonstrated by complete or partial restoration of IR and Akt1 kinase activity." (PMID 22046295, 2011). "Among these, seven key targets (JUN, AKT1, ESR1, CASP33, TNF, SRC, and IL6) were found to have the highest network connectivity, indicating their central role in treating diabetes with Chaga." (PMID 40508014, 2025). "Key targets such as JUN, AKT1, ESR1, CASP3, TNF, SRC, and IL6 were identified as central regulators in diabetes-related pathways, with molecular docking confirming strong binding interactions between Chaga-derived phytochemicals and these targets." (PMID 40508014, 2025). "The results offer us a comprehensive understanding of the therapeutic effects of previously identified target proteins, including AKT1, IL6, PPARG, JUN, CASP3, EGFR, and PTGS2, in the context of diabetes intervention." (PMID 39707185, 2024). "We selected AKT1, IL-6, and PPARG as the core targets for gut microbiota metabolite regulation of diabetes based on their highest DC values." (PMID 39707185, 2024). "Gut microbiota metabolites primarily exert their therapeutic effects on diabetes through the IL6, AKT1, and PPARG targets." (PMID 39707185, 2024). "The PPI network indicated AKT1, IL-6 and PPARG as hub genes that are involved in the mechanism of diabetes." (PMID 39707185, 2024). "Among the top 20 core targets, 5 targets (STAT3, PIK3CA, AKT1, EGFR and VEGFA) were closely related to diabetes." (PMID 38921004, 2024). "Meanwhile, the pathways involved in the treatment of diabetes complicated by AS by XFZYD are related to the VEGFA signaling pathway, AKT1 signaling pathway, and CCL2 signaling pathway." (PMID 35960089, 2022). "AKT1 is ubiquitously expressed, while AKT2 is predominantly expressed in brown fat and the heart, correlating with the role of AKT2 in diabetes and glucose metabolism." (PMID 21869924, 2011). "In addition to the potential for reducing adiposity, we believe that the improved insulin sensitivity in Mstn−/−, muscle-DN, and constitutively active Akt1 mice suggests that altering metabolism by increasing muscle mass might be a promising strategy for treating diabetes and the metabolic syndrome." (PMID 19295913, 2009). "Notably, the PI3K-Akt signaling pathway, a critical pathway in diabetes, was enriched with additional key targets, including IL6, HSP90AA1, FN1, MAPK1, AKT1, PIK3R1, and MAPK3." (PMID 40170727, 2025).
diabetes (continued). "Additionally, myricetin and rutin have been shown to modulate various diseases, including diabetes, atherosclerosis, and inflammation-related disorders, through the STAT3, AKT1, and PIK3R1 signaling pathways." (PMID 40356949, 2025). "Subsequently, we selected IL6, AKT1 and PPARG as core targets for the treatment of diabetes." (PMID 39707185, 2024). "In older adults with and without diabetes, higher levels of serine/threonine-protein kinase (AKT1) phosphorylation (pT308AKT1/total AKT1) in the brain were associated with lower levels and faster decline in global cognition." (PMID 38029396, 2024). "In addition, the cytoHubba plug-in has identified four key targets (HSP90AA1, AKT1, SRC, and MAPK1) that have a significant connection to the pathogenesis and treatment of type 2 diabetes mellitus." (PMID 38031191, 2023). "This suggests that inhibition of diabetes-induced retinal molecular modifications and pathological changes in the RPE of Akt2 cKO mice may be due to the upregulation of Akt1 and the downstream inhibition of the GSK3β/NF-κB regulated inflammatory response." (PMID 36229454, 2022). "Prominent genes were RHOA, AKT1, RAC1, MDM2, CDKN1A, and VEGFA, which play important roles in TGF-beta and mTOR signaling (KEGG database), signaling by Wnt and by NOTCH (Reactome database), and in complications in diabetes mellitus (DisGeNET database)." (PMID 35742976, 2022). "To investigate further how the lack of Akt2 in the RPE protects the retina from diabetes-induced abnormalities, we focused on Akt1 and its downstream targets." (PMID 36229454, 2022). "The expression of PI3K and AKT1 was inhibited by diabetes, while exogenous H2S reversed the changes, suggesting exogenous H2S activated the PI3K/AKT1 signaling pathway suppressed by diabetes." (PMID 34201520, 2021). "In our prior work in the same group of 150 persons with and without diabetes, we found that AKT phosphorylation (pT308AKT1/total AKT1, based on ELISA) was associated with another common neuropathology of aging, AD neuropathology, including amyloid and tangles." (PMID 33858515, 2021). "Unlike Akt1 and Akt3 KO mice, Akt2 KO mice develop diabetes and are insulin resistant." (PMID 40141412, 2025). "The ten important active constituents were chosen for molecular docking verification with the key targets TNF, AKT1, EGFR, and GSK3β (the core intersection target of the PPI network and Component-pathway-target network), which are considered potential targets in the treatment of diabetes." (PMID 40076380, 2025). "While studies focusing on the distinct roles of the Akt1 and Akt2 isoforms in RPE during the development of DR have not been published, the idea that Akt may be involved in RPE cell EMT and retinal fibrosis in diabetes has recently surfaced." (PMID 37443129, 2023). "Further correlation analysis indicated the key molecules involved in PI3K-AKT signaling pathway, such as AKT1, AKT2, PIK3R1, and PIK3R2, showed significant positive correlations with AFAP1L2, and in which AKT1 also showed elevated expression in patients without diabetes history." (PMID 36434634, 2022). "We found that in the Akt2fl/fl samples, diabetes increased the level of phospho-Akt2 (but not total Akt2) and increased the ratio of phospho-NF-κB p65/total NF-κB p65, while decreasing phospho-Akt1 and the proportion of phospho-GSK3β/total GSK3β as compared to Akt2fl/fl nondiabetic controls." (PMID 36229454, 2022).
diabetes (continued). "Our results uncovered that AS-IV can protect retinal cells against diabetes induced retinopathy, which may act on target proteins AKT1, CASP3 and HIF1α, VEGFA, IL6, IL1β, SRC and CTNNB1, and might be involved in the regulation of PI3K-AKT signaling pathway." (PMID 35814228, 2022). "Haplodeficiency of AKT1 in mice within an AKT2 null background can convert a pre-diabetic phenotype to overt type 2 diabetes, which is reversible by haplodeficiency of PTEN, whereas AKT3 does not appear to contribute significantly to diabetes." (PMID 22680924, 2012).
non-small cell lung carcinoma (226 papers, 2002 to 2026). A group of at least three distinct histological types of lung cancer, including non-small cell squamous cell carcinoma, adenocarcinoma, and large cell carcinoma. "Activation of Akt1 signaling pathway is associated with progression of non-small cell lung cancer (NSCLC) and enhanced expression of programmed death ligand-1 (PD-L1), an immunoregulatory protein." (PMID 30400835, 2018). "AKT1 rs3803300, rs1130214, and rs2494732 have significant effects on survival in non-small cell lung cancer patients: patients with the rs3803300 G allele and rs1130214 G allele had shorter overall survival (OS) and disease-free survival (DFS) times." (PMID 26317520, 2015). "Carriers of the (GT+GG) genotype of AKT1 rs2498804 or the CT/TT genotype of AKT1 rs2494732 were found to have an increased risk of brain metastasis of non-small cell lung cancer." (PMID 26317520, 2015). "Additionally, AKT1 polymorphisms were found to predict treatment response and clinical outcome in patients with esophageal and non-small cell lung cancer." (PMID 24632578, 2014). "In this study, we used high resolution melting (HRM) analysis to screen the AKT1 E17K mutation in a panel of 219 non-small cell lung cancer (NSCLC) tumour biopsies to determine if this mutation may occur in NSCLC." (PMID 18611285, 2008). "AKT, alternatively known as AKT1, has five widely studied polymorphisms (rs3803300, rs1130214, rs2494732, rs2498804, and rs1130233); the first four have been linked to the risk or prognosis of nasopharyngeal carcinoma, oral squamous cell carcinoma, and non-small cell lung cancer." (PMID 26317520, 2015). "Exosomal miR-425-3p in cisplatin-resistant non-small cell lung cancer (NSCLC) promotes autophagy activation by targeting the AKT1/mTOR pathway, leading to cisplatin resistance in sensitive cells." (PMID 40490663, 2025). "Jin’s research indicated that the potential of CRTAC1 to augment the chemosensitivity of non-small cell lung cancer to cisplatin is attributed to its ability to induce RyR-mediated calcium release and suppress Akt1 expression." (PMID 38755183, 2024). "In particular, they showed that inhibition of AKT1 effectively sensitized non-small cell lung cancer cell lines to IR by inhibiting DNA-PKcs-dependent DNA DSB repair." (PMID 33266502, 2020). "AKT1 is a regulatory component in the homologous recombination repair of DNA-DSB in a Rad51-dependent manner in non-small cell lung cancer cells." (PMID 32711558, 2020). "MiR-124a can inhibit proliferation, glycolysis, and energy metabolism by potentially targeting the AKT1/2-glucose transporter 1/hexokinase II in non-small cell lung cancer cells." (PMID 32974168, 2020). "A previous study from our laboratory showed that AKT1-siRNA knockdown in the non-small cell lung cancer cell line A549 significantly reduced both Rad51 protein levels and foci formation." (PMID 31847370, 2019). "Consistent with our observations, previous reports have also implied the profound significance of Akt1 and 2 gene expression in the prognosis of different cancers such as esophageal squamous cell carcinoma and non-small cell lung carcinoma." (PMID 31252679, 2019). "Isoform-specific Akt abnormalities have been reported in many cancer cells, such as the overexpression of Akt1 in thyroid and non-small cell lung cancers, Akt2 and Akt3 in malignant glioma, and Akt3 in melanoma, ovarian, and breast cancer." (PMID 28483982, 2017). "Here, we report our experience using next generation sequencing (NGS) to examine AKT1, BRAF, EGFR, ERBB2, KRAS, NRAS, and PIK3CA genes in 1006 non-small cell lung cancers in a clinical diagnostic setting." (PMID 29228562, 2017). "With this Akt1-construct we generated stable cell clones of MCF10A mammary epithelial cells and A549 non small cell lung cancer (NSCLC) cells expressing constitutively active farnesylated (CA) Akt1." (PMID 12373610, 2002).
non-small cell lung carcinoma (continued). "Similarly, the downregulation of AKT1 has been shown to enhance the chemosensitivity of multiple tumor cells, including non-small-cell lung cancer, esophageal squamous cell carcinoma, and head and neck squamous cell carcinoma." (PMID 37791141, 2023). "Furthermore, they also observed that hsa-miR-548 was involved in the migration and invasion of non-small cell lung cancer cells by targeting the AKT1 signaling pathway." (PMID 31105742, 2019). "Phosphorylation of at least two of the three further known Akt target proteins Proline-rich AKT1 substrate 1 (PRAS40), tuberous sclerosis 2 (TSC2) and TBC1 Domain Family Member 4 (TBC1D4) in non-small cell lung cancer cell lines also required Akt1-phosphorylation at T308 for their activation." (PMID 29562639, 2018). "For example, up-regulation of lncRNA LINC00152 promoted the development of non-small cell lung cancer (NSCLC) through activating EGFR, which promoted tumor cell proliferation by increasing the activity of the PI3K/Akt (AKT serine/threonine kinase 1) pathway." (PMID 36497250, 2022). "Inhibition of AKT1 enhanced migration and invasion in KRAS- or EGFR-mutant non-small cell lung cancer (NSCLC) cells." (PMID 28765579, 2017). "AKT1, as a subtype of AKT, may play an important role in the occurrence and development of non-small cell lung cancer." (PMID 37533633, 2023).